GNG11 (G protein subunit gamma 11)
Description:
Guanine nucleotide-binding proteins (G proteins) are involved as a modulator or transducer in various transmembrane signaling systems. The beta and gamma chains are required for the GTPase activity, for replacement of GDP by GTP, and for G protein-effector interaction.
Synonyms: GNGT11; HG3H1
Tractability: Antibody: UniProt places it where antibodies can reach, with high confidence; its Gene Ontology location is reachable by antibodies, with high confidence. PROTAC: ubiquitination databases record sites on it.
Gene: Protein-coding gene on chromosome 7 (93,921,735 to 93,928,610, forward strand). Ensembl gene ENSG00000127920.
Subcellular location: Cell membrane
Pathways (Reactome):
Signal Transduction: Ca2+ pathway; Extra-nuclear estrogen signaling; G alpha (12/13) signalling events; G alpha (i) signalling events; G alpha (q) signalling events; G alpha (s) signalling events; G alpha (z) signalling events; G beta:gamma signalling through BTK; G beta:gamma signalling through CDC42; G beta:gamma signalling through PI3Kgamma; G beta:gamma signalling through PLC beta; G-protein activation; GPER1 signaling; Glucagon-type ligand receptors
Hemostasis: ADP signalling through P2Y purinoceptor 1; ADP signalling through P2Y purinoceptor 12; Prostacyclin signalling through prostacyclin receptor; Thrombin signalling through proteinase activated receptors (PARs); Thromboxane signalling through TP receptor
Metabolism: Adrenaline,noradrenaline inhibits insulin secretion; Glucagon signaling in metabolic regulation; Glucagon-like Peptide-1 (GLP1) regulates insulin secretion
Neuronal System: Activation of G protein gated Potassium channels; Inhibition of voltage gated Ca2+ channels via Gbeta/gamma subunits; Presynaptic function of Kainate receptors
Cellular responses to stimuli: High laminar flow shear stress activates signaling by PIEZO1 and PECAM1:CDH5:KDR in endothelial cells
Disease: ADORA2B mediated anti-inflammatory cytokines production
Metabolism of proteins: Cooperation of PDCL (PhLP1) and TRiC/CCT in G-protein beta folding
Transport of small molecules: Vasopressin regulates renal water homeostasis via Aquaporins
Gene Ontology:
Molecular function: protein binding; G-protein beta-subunit binding; GTPase activity
Biological process: G protein-coupled receptor signaling pathway; signal transduction
Cellular component: heterotrimeric G-protein complex; plasma membrane
Homologues: Orthologues: chimpanzee GNG11 (100% identical), mouse Gng11 (100% identical), rabbit GNG11 (100% identical), rat Gng11 (100% identical), dog GNG11 (99% identical), macaque GNG11 (99% identical), pig GNG11 (99% identical), guinea pig GNG11 (97% identical), tropical clawed frog gngt1 (79% identical), zebrafish gngt1 (62% identical), Drosophila melanogaster Ggamma1 (37% identical). Paralogues in human: GNGT1 (77% identical), GNGT2 (60% identical), GNG12 (36% identical), GNG3 (34% identical), GNG7 (33% identical), GNG2 (32% identical), GNG4 (32% identical), GNG8 (29% identical), GNG10 (27% identical), GNG5 (27% identical), GNG5B (25% identical).
Diseases named in the same sentence as GNG11 in open-access papers:
GNG11 is named in the same sentence as 42 diseases in open-access papers, as found by Europe PMC text mining. Sharing a sentence is not in itself a finding about the gene and the disease. The quoted sentences say what the papers report.
lung cancer (6 papers, 2019 to 2025). A malignant neoplasm involving the lung. "Current research on GNG11 is not comprehensive and mainly focuses on human diseases such as intestinal disease, lung cancer, bladder cancer, and breast cancer, with research on GNG11 in cows being underrepresented." (PMID 38271979, 2024). "Previous studies on GNG11 have predominantly been confined to lung cancer-related research." (PMID 41244534, 2025). "Notably, certain genes, such as CTLA4, MZB1, NIP7, and BUB1B in ADC, as well as GNG11 and CCNB2 in SCC, were found to be associated with tumor size, adding a crucial dimension to our understanding of lung cancer biology." (PMID 38612418, 2024). "However, the specific biological function of GNG11 in lung cancer still remains unknown." (PMID 31877723, 2019).
breast carcinoma (5 papers, 2018 to 2024). "Moreover, according to the prognostic scoring method we developed, GNG11 was associated with poor survival by presenting low scores in breast cancer and high scores in colorectal cancer." (PMID 37489460, 2023).
ovarian carcinoma (4 papers, 2023 to 2025). A malignant neoplasm originating from the surface ovarian epithelium. "The expression of GNG11 mRNA is down-regulated in ovarian cancer patients, and its high expression is associated with poor prognosis." (PMID 39869563, 2025). "GNG11 may play a crucial role in the biological process of ovarian cancer through the ECM-receptor interaction pathway." (PMID 39869563, 2025).
colon cancer (2 papers, 2020 to 2023). "In line with other studies, according to our study, the GNG11 gene was downregulated and highly methylated in both breast and colon tumor tissues compared to normal tissues." (PMID 37489460, 2023).
lung adenocarcinoma (2 papers, 2017 to 2023). A carcinoma that arises from the lung and is characterized by the presence of malignant glandular epithelial cells. "We found that GNG11 may exert suppressor functions in the tumorigenesis of lung adenocarcinoma." (PMID 29285217, 2017). "Survival curve analysis revealed that lung adenocarcinoma patients with high expression of ZDHHC9, BTNL9, GNG11 or CPED1 are correlated with better survival outcomes." (PMID 29285217, 2017). "The mRNA expression of BTNL9, GNG11, or CPED1 is downregulated in lung adenocarcinoma when compared to normal tissue, and ZDHHC9 is upregulated." (PMID 29285217, 2017). "In the GSE10072 array, GNG11 and CPED1 expression is downregulated in lung adenocarcinoma." (PMID 29285217, 2017). "The analysis of the effects from each gene expression on survival outcome indicated that 6 genes (AGR2, SPDEF, CDKN2A, CLDN3, SFN, and PHLDA2) play oncogenic roles, and 7 genes (PDK4, FMO2, CPED1, GNG11, IL33, BTNL9, and FABP4) act as tumor suppressors in lung adenocarcinoma." (PMID 29285217, 2017).
splenic marginal zone lymphoma (2 papers, 2015 to 2024). Splenic marginal zone lymphoma is a rare, indolent B-cell non-Hodgkin lymphoma characterized by abnormal clonal proliferation of mature B-lymphocytes with involvement in the spleen, bone marrow and, frequently, the blood. "GNG11 is downregulated in splenic marginal zone lymphomas, suggesting that upregulated GNG11 has an inhibitory effect on the proliferation of B cells." (PMID 38932372, 2024).
Alzheimer disease (1 paper, 2011). A progressive, neurodegenerative disease characterized by loss of function and death of nerve cells in several areas of the brain leading to loss of cognitive function such as memory and language. "Novel candidates are associated with neurodegenerative disorders including Alzheimer's disease (VSNL1), prion disease (SCRG1, HSPH1, HSPA5 and CTR9) and age-related degeneration (GAS6 and GNG11)." (PMID 21569303, 2011).
ankylosing spondylitis (1 paper, 2015). An autoimmune chronic inflammatory disorder characterized by inflammation in the vertebral joints of the spine and sacroiliac joints. "However, neither GNG11 nor S100P have been reported to be associated with ankylosing spondylitis yet." (PMID 25688367, 2015).
cervical cancer (1 paper, 2020). A primary or metastatic malignant neoplasm involving the cervix. "In a recent study, GNG11 resulted as the best candidate protein to have an inhibitory effect on the cervical cancer, underlining the important role in a female organ." (PMID 32784482, 2020).
hypertrophic cardiomyopathy (1 paper, 2025). A condition in which the myocardium is hypertrophied without an obvious cause. "We also observed enrichment in pathways associated with circadian entrainment (e.g., GNG11, GUCY1B1) and hypertrophic cardiomyopathy (e.g., ITGB3, ITGA2B, IL6), suggesting systemic disruptions in PitNET PBMCs." (PMID 41253784, 2025).
leukemia (1 paper, 2011). A malignant (clonal) hematologic disorder, involving hematopoietic stem cells and characterized by the presence of primitive or atypical myeloid or lymphoid cells in the bone marrow and the blood. "Remaining candidates (N = 62) comprised BDNF-related genes (SST), MAPK-pathway genes (KRAS, IGF1R, GNG11 and RAP1A), genes related with leukemia (SFRP1) and Rho-Proteins (DHCR7 and RAB21)." (PMID 21569303, 2011).
lung squamous cell carcinoma (1 paper, 2020). "Previous studies showed that in lung squamous cell carcinoma GNG11 was a novel hub gene in module-related tumor size, and the low mRNA expression of GNG11 was associated with the higher overall survival rate for patients." (PMID 33115518, 2020).
lymph node metastasis (1 paper, 2025). "The findings (Table-II) underscored a significant association between low positive expression levels of GNG11 and tumor size (P=0.0068), FIGO stage (P=0.0282), and lymph node metastasis (P=0.0101) in CC patients." (PMID 41244534, 2025). "Cox regression analysis revealed that FIGO stage (P=0.014), lymph node metastasis (P=0.002), and GNG11 expression (P=0.026) emerged as independent prognostic indicators for OS in CC patients." (PMID 41244534, 2025). "Multivariate Cox analysis revealed that FIGO stage (P=0.014), lymph node metastasis (P=0.002), and GNG11 positive expression (P=0.026) were independent prognostic factors for OS (Table-IV)." (PMID 41244534, 2025). "Furthermore, multivariate Cox analysis indicates that tumor size, lymph node metastasis, and GNG11 positive expression level maintain independent correlations with OS in CC patients." (PMID 41244534, 2025). "Further analysis of prognostic factors affecting OS in CC patients reveals that tumor size, FIGO stage, lymph node metastasis, and the positive expression level of GNG11 are significantly related to OS, whereas age, histological type, and HPV infection are not linked to patient survival." (PMID 41244534, 2025).
lymphoma (1 paper, 2017). A malignant (clonal) proliferation of B- lymphocytes or T- lymphocytes which involves the lymph nodes, bone marrow and/or extranodal sites. "GNG11 is a lipid-anchored protein, which has been reported to inhibit cell growth and regulate cellular senescence in lymphoma." (PMID 29285217, 2017).
mastitis (1 paper, 2020). Inflammation of breast tissue during lactation or postpartum due to an obstructed duct or infection. "GNG11 and GNGT1 code for G proteins, which function as key attributes of innate immune responses, and these are involved in functions relating to mastitis resistance." (PMID 32580275, 2020).
metastasis (1 paper, 2025). The spread or migration of cancer cells from one part of the body (where they first appeared) to another. "A significant correlation was observed between low positive expression of GNG11 and tumor size (P=0.0068), FIGO stage (P=0.0282), and lymph node metastasis (P=0.0101) in CC patients." (PMID 41244534, 2025).
pancreatic cancer (1 paper, 2023). "These genes were overlapped with 9,170 DEGs in PAAD, which were obtained by comparing the mRNA expression profile between pancreatic cancer in TCGA and the normal pancreas in GTEx; six specific genes were found, including VWF, GNG11, FGF7, TNXB, IL3RA, and LPAR1." (PMID 37070074, 2023).
post-traumatic stress disorder (1 paper, 2020). An anxiety disorder precipitated by an experience of intense fear or horror while exposed to a traumatic (especially life-threatening) event. "Another module downregulated in the early adversity group was related to platelet activation and wound healing (hub genes: GP9, CMTM5, TUBB1, GNG11, PF4), and resembled a co-expression module previously found over-expressed in post-traumatic stress disorder resilient soldiers." (PMID 32066736, 2020).
sarcopenia (1 paper, 2020). Progressive decline in muscle mass due to aging which results in decreased functional capacity of muscles. "We observed that the expression of IL1B, BAK1 and SOD1 were significantly increased, while the expression of CDH1, GNG11 and ZAP70 were dramatically decreased in sarcopenia samples compared to those in the controls." (PMID 32226296, 2020).
viral myocarditis (1 paper, 2021). Myocarditis that is caused by an infection with a viral agent. "GSEA analysis demonstrated that spliceosome and viral myocarditis were correlated with GNG11." (PMID 34178627, 2021).
tumor (17 papers, 2012 to 2025). "The LC-BC CCPs formed have no more than 12 nodes and identified only seven genes (EDNRB, CDKN2A, VEGFD, FOS, GNG11, TGFBR2, and BIRC5) compromised in signaling pathways associated with the acquisition of tumor characteristics." (PMID 36101460, 2022). "ReactomeFIViz enrichment analysis in Cytoscape showed an association of seven (EDNRB, CDKN2A, VEGFD, FOS, GNG11, TGFBR2, and BIRC5) of the forty-four nodes of the LC-BC CCPs with signaling pathways related with the acquisition of tumor characteristics." (PMID 36101460, 2022). "CTLA4, MZB1, NIP7, and BUB1B in ADC, as well as GNG11 and CCNB2 in SCC, are novel top hub genes in modules associated with tumour size, SUVmax, and recurrence-free survival." (PMID 31877723, 2019). "In TβRII KO tumor epithelium compared with TβRIIfl/fl epithelium, Igfbp4 and Tspan13 expression was upregulated while Col1α2, Bmp7, Gng11, Vcan, Tmeff1, and Dsc2 expression was downregulated." (PMID 22748014, 2012). "Univariate analysis identified tumor size (P<0.0001), FIGO stage (P=0.0193), lymph node metastasis (P=0.0087), and GNG11 positive expression (P=0.0001) as prognostic factors influencing OS (Table-III)." (PMID 41244534, 2025). "We classified UM tumor cells into six distinct subclusters based on marker gene expression: C0 WSB1+ TCs, C1 EEF1A1+ TCs, C2 HSPB7+ TCs, C3 XIST+ TCs, C4 GNG11+ TCs, and C5 PCOLCE+ TCs." (PMID 39635521, 2024). "According to the data on THPA, most of these genes (VWF, GNG11, FGF7, and IL3RA) were also higher in PAAD tissues at the protein level (compared to non-tumor tissues)." (PMID 37070074, 2023). "To further select the key genes in the complex network, we analyzed all of genes integrating with the clinical categories and found that TGFβ2, GNG11, PDGFB, and ITGA5 were changed among different patients’ tumor stages, states, T categories, and grades." (PMID 33115518, 2020). "A higher level of GDP but not GTP was accompanied by downregulation of GPCR‐related genes (GNG11 and GNA14) in the tumours of both LUSC and LUAD." (PMID 31461552, 2019). "KEGG and PPI analyses revealed that GNG11, LPAR1, and AGTR1, as key factors in cancer biological processes, are significantly downregulated in CC, suggesting their potential role as tumor suppressor genes, which is of profound importance in unveiling the pathogenesis of CC." (PMID 41244534, 2025).
cancer (9 papers, 2017 to 2025). A tumor composed of atypical neoplastic, often pleomorphic cells that invade other tissues. "On the whole, therefore, findings available suggest that GNG11 could be involved in different signaling pathways within cancer cells and TME." (PMID 35120576, 2022). "We found that 30 of these genes which included Nckap1l, Ncf1, Pla2g15, Unc93b1, Lrrc33, Rgs10, Gmfg, Rbm25, C3ar1, Ccdc88b, Fam105a, Gng11, Phc1, Rasa4, Dag1, Tyrobp, Tmsb4x, Cfp, Prkd1, Gp49a, Trem2, C1qc, Lyz2, Igfbp7, Rab30, Cxcl16, Egfl7, Ube2r2, Pltp, and Cfb, showed a relation with cancer." (PMID 32812032, 2020). "A literature survey about significant biomarkers highlighted in survival analysis revealed that GNG11, CBX2, CDKN3, ARHGEF10, CLN8, SEC61G and PTDSS1 genes present similar survival and prognostic behaviors in the specified cancers." (PMID 37489460, 2023). "The central gene is PIK3R1 in Module 0, which module contains eight DEGs related to classical cancer pathways (FCER1A, GNG11, IGF1, LIFR, PDK4, PIK3R1, RCAN2, and UGCG)." (PMID 31119098, 2019). "First, although GNG enzymes were previously assumed to be absent from cancer cells that did not arise in gluconeogenic organs (liver, kidney), several studies demonstrated their expression in diverse cancers as mediators of abbreviated forms of GNG11,12,55." (PMID 38783087, 2024).
infection (2 papers, 2017 to 2025). The state of being infected such as from the introduction of a foreign agent such as serum, vaccine, antigenic substance or organism. "We identified ten NK subgroup-specific marker molecules (Kcnj8, Cmah, Ccnd2, Cx3cr1, Thy1, Tnfrsf9, Zbtb20, Gng11, CD226, Egr3) from C0 to C9 and assessed their expression changes during infection using RT-qPCR." (PMID 40244063, 2025). "As infection progressed in the adult-derived DCs, similar expression changes as those observed in cord DCs were observed for all GPCR genes, but GNG11 and HCAR3 that did not exhibit an altered gene expression." (PMID 28993767, 2017).
cardiac disease (1 paper, 2023). "GNG11 plays a key role in heart rhythm regulation and is associated with cardiac disease risk." (PMID 37489460, 2023).
GNG11 also shares sentences with these, for which no sentence is quoted: bladder cancer (2 papers); atrial fibrillation (1); Atrophy (1); colorectal cancer (1); coronary artery disease (1); Crohn disease (1); glioma (1); Huntington disease (1); intestinal disease (1); multiple sclerosis (1); Obesity (1); Parkinson disease (1); prion disease (1); pulmonary hypertension (1); serous ovarian cancer (1); triple-negative breast carcinoma (1); ulcerative colitis (1); viral infection (1).